GABRR2 (gamma-aminobutyric acid type A receptor subunit rho2)
Description:
Rho subunit of the pentameric ligand-gated chloride channels responsible for mediating the effects of gamma-aminobutyric acid (GABA), the major inhibitory neurotransmitter in the brain (By similarity). Rho-containing GABA-gated chloride channels are a subclass of GABA(A) receptors (GABAARs) entirely composed of rho subunits, where GABA molecules bind at the rho intersubunit interfaces (By similarity). When activated by GABA, rho-GABAARs selectively allow the flow of chloride anions across the cell membrane down their electrochemical gradient (By similarity). Rho-2 GABAARs may contribute to the regulation of glial development in the cerebellum by controlling extrasynaptic transmission. Rho-2 GABAARs are also involved in neuronal tonic (extrasynaptic) and phasic (synaptic) transmission in the Purkinje neurons of the cerebellum (By similarity). Rho-2 GABAARs expressed in retina may play a role in retinal neurotransmission (By similarity).
Tractability: Small molecule: it belongs to a druggable protein family. Antibody: its Gene Ontology location is reachable by antibodies, with high confidence; UniProt places it where antibodies can reach, with medium confidence; UniProt predicts a signal peptide or a membrane-spanning region. PROTAC: a small molecule that binds it is known.
Target class: Ion channel; GABA-A receptor; Ligand-gated ion channel
Gene: Protein-coding gene on chromosome 6 (89,254,464 to 89,315,299, reverse strand). Ensembl gene ENSG00000111886.
Subcellular location: Postsynaptic cell membrane; Cell membrane
Pathways (Reactome):
Neuronal System: GABA receptor activation
Gene Ontology:
Molecular function: GABA-A receptor activity; GABA-gated chloride ion channel activity; extracellular ligand-gated monoatomic ion channel activity; monoatomic ion channel activity; protein domain specific binding; transmembrane signaling receptor activity; transmitter-gated monoatomic ion channel activity involved in regulation of postsynaptic membrane potential
Biological process: chemical synaptic transmission; chloride transmembrane transport; signal transduction; synaptic transmission, GABAergic; monoatomic ion transmembrane transport; monoatomic ion transport; regulation of postsynaptic membrane potential
Cellular component: GABA-A receptor complex; GABA-ergic synapse; plasma membrane; postsynaptic membrane; intracellular vesicle; membrane
Genetic constraint (gnomAD): Loss-of-function variants: 33 observed, 43.91 expected, observed/expected ratio (o/e) 0.75, 90% interval 0.57 to 1. The upper end of that interval is the gene's LOEUF score, 1, which puts it in group 4 of 6, group 1 being the genes least tolerant of losing a copy. Missense variants: 545 observed, 582.35 expected, observed/expected ratio (o/e) 0.94, 90% interval 0.87 to 1. Synonymous variants: 193 observed, 223.86 expected, observed/expected ratio (o/e) 0.86, 90% interval 0.77 to 0.97.
Homologues: Orthologues: chimpanzee UBE2J1 (99% identical), macaque GABRR2 (98% identical), rabbit GABRR2 (94% identical), pig GABRR2 (93% identical), rat Gabrr2 (91% identical), mouse Gabrr2 (90% identical), guinea pig GABRR2 (89% identical), dog GABRR2 (86% identical), tropical clawed frog GABRR2 (82% identical), zebrafish gabrr2b (72% identical), zebrafish gabrr2a (66% identical). Paralogues in human: GABRR1 (72% identical), GABRR3 (59% identical), GABRB1 (39% identical), GABRB2 (38% identical), GABRB3 (38% identical), GLRA3 (35% identical), GLRA2 (34% identical), GLRA1 (34% identical), GABRG1 (32% identical), GABRG3 (32% identical), GABRA4 (32% identical), GABRD (32% identical), and 33 more.
Diseases named in the same sentence as GABRR2 in open-access papers:
GABRR2 is named in the same sentence as 13 diseases in open-access papers, as found by Europe PMC text mining. Sharing a sentence is not in itself a finding about the gene and the disease. The quoted sentences say what the papers report.
alcohol dependence (2 papers, 2014 to 2025). Physical and psychological dependence on alcohol. "Ultimately, GABAA ρ receptors may play a role in several in vivo effects, including ethanol intake, that are relevant for alcoholism and may explain the association of polymorphisms linked with human GABRR1 and GABRR2 genes and alcohol dependence." (PMID 24454882, 2014). "Similarly, Gabrr2, which encodes the GABA-A receptor subunit rho2, has been associated with alcohol dependence." (PMID 41002437, 2025).
alcohol use disorder (1 paper, 2019). "Interestingly, genetic deletion of GABRR1 potentiated sedative motor effects of ethanol in mice and SNPs in GABRR1 and GABRR2 genes are associated with alcohol use disorder." (PMID 31717954, 2019).
Anxiety (1 paper, 2021). Intense feelings of nervousness, tension, or panic often arise in response to interpersonal stresses. "Altered expression of Gabrr2, Gabra6 and Gabra2 is implicated in the pathogenesis of anxiety and depression." (PMID 34448534, 2021).
nicotine addiction (1 paper, 2022). "This then shifted, where day 4 was enriched for the nicotine addiction KEGG pathway, a pathway associated with nicotine-induced alterations in glutamatergic and GABAergic receptors (e.g., GRIN1 and GABRR2) on GABAergic MSNs." (PMID 35563715, 2022).
cancer (1 paper, 2020). A tumor composed of atypical neoplastic, often pleomorphic cells that invade other tissues. "Expression of GABRG3, GABRQ, GABRE, and GABRR2 is correlated with inhibition of growth phenotypes in cell lines and with favorable patient outcomes (Broad Institute of MIT & Harvard, firebrowse.org), while expression of other transcripts (GABRB2, GABRP) is associated with cancer progression." (PMID 33187258, 2020).
GABRR2 also shares sentences with these, for which no sentence is quoted: alcoholism (1 paper); autism (1); bipolar disorder (1); cardiac arrhythmia (1); depression (1); epilepsy (1); myopia (1); schizophrenia (1).